RNU6-1147P (RNA, U6 small nuclear 1147, pseudogene)
Gene: Small nuclear RNA gene on chromosome 2 (127,316,873 to 127,316,979, forward strand). Ensembl gene ENSG00000200250.
Homologues: Orthologues: chimpanzee U6 (99% identical), macaque U6 (91% identical), pig U6 (73% identical). Paralogues in human: RNU6-15P (91% identical), RNU6-10P (90% identical), RNU6-12P (90% identical), RNU6-13P (90% identical), RNU6-31P (90% identical), RNU6-32P (90% identical), RNU6-41P (90% identical), RNU6-1 (89% identical), RNU6-1060P (89% identical), RNU6-17P (89% identical), RNU6-18P (89% identical), RNU6-19P (89% identical), and 1287 more.